PCDHB17P (protocadherin beta 17 pseudogene)
Synonyms: PCDH-psi1; formerly PCDHB17
Gene: Transcribed unprocessed pseudogene on chromosome 5 (141,155,996 to 141,158,388, forward strand). Ensembl gene ENSG00000255622.
Diseases named in the same sentence as PCDHB17P in open-access papers:
PCDHB17P is named in the same sentence as 3 diseases in open-access papers, as found by Europe PMC text mining. Sharing a sentence is not in itself a finding about the gene and the disease. The quoted sentences say what the papers report.
breast carcinoma (2 papers, 2021 to 2022). "Kaplan-Meier survival analysis indicated that increased PCDHB17P expression in breast cancer was significantly associated with a lower rate of overall survival and disease-free survival." (PMID 34350110, 2021). "In the present study, we firstly figured out a novel lncRNA PCDHB17P, which was highly expressed in breast cancer tissues and also associated with poor prognosis." (PMID 34350110, 2021). "In this basis, we wondered whether PCDHB17P was implicated in breast cancer development." (PMID 34350110, 2021). "PCDHB17P is highly expressed in breast cancers and promotes cancer by competing with endogenous RNA." (PMID 35712126, 2022). "In the present study, we investigated the role of PCDHB17P in breast cancer and found its promotion effect on migration and tumor-related angiogenesis." (PMID 34350110, 2021). "What’s more, the expression of MELK and PCDHB17P were positively correlated in Breast cancer tissues." (PMID 34350110, 2021). "Subcellular fractionation analysis-verified PCDHB17P was localized mainly in the cytoplasm of breast cancer cells." (PMID 34350110, 2021). "MiR-145-3p was significantly decreased in breast cancer samples, which was negatively correlated to the expression of PCDHB17P." (PMID 34350110, 2021). "Analysis based on the TCGA dataset presented the up-regulation of PCDHB17P in breast cancer samples." (PMID 34350110, 2021). "In summary, the present study firstly revealed that PCDHB17P was upregulated in breast cancer tissues and cell lines, MELK mediated PCDHB17P-induced promotion on breast cancer metastasis and angiogenesis by sponging miR-145-3p." (PMID 34350110, 2021). "In vitro function experiments demonstrated that MELK knockdown or miR-145-3p mimics partially rescued the stimulative effects of PCDHB17P overexpression on breast cancer cells migration, invasion, and angiogenesis." (PMID 34350110, 2021). "Transwell and Wound Healing assays demonstrated that breast cancer cells were enhanced by PCDHB17P overexpression while weakened by PCDHB17P knockdown." (PMID 34350110, 2021). "Knockdown of PCDHB17P remarkably suppressed migration and invasion, as well as tube formation ability of breast cancer cells." (PMID 34350110, 2021). "Here, we demonstrated that lncRNA PCDHB17P was up-expressed in human breast cancer tissues and cell lines." (PMID 34350110, 2021). "Meanwhile, PCDHB17P overexpression-derived CM significantly promoted the migration and invasion of HUVEC cells, whereas CM from PCDHB17P knockdown breast cancer cells weaken the migratory and invasive abilities of HUVEC cells." (PMID 34350110, 2021). "In our study, based on the analysis of breast cancer TCGA datasets, we identified a breast cancer-related lncRNA PCDHB17P, which was apparently highly expressed in breast cancer tissues compared with the normal tissues." (PMID 34350110, 2021). "When exposed the CM to human umbilical vascular endothelial cells (HUVEC) cells, CM from PCDHB17P overexpression breast cancer cells promoted the tube formation ability, whereas the angiogenesis was inhibited by the CM from PCDHB17P-silenced breast cancer cells." (PMID 34350110, 2021). "To elucidate whether PCDHB17P is involved in the breast cancer development, we analyzed the correlation of PCDHB17P expression with clinical pathology factors." (PMID 34350110, 2021). "Additionally, PCDHB17P expression was elevated in frozen breast cancer tissues compared with that in the adjacent normal tissues by RT-qPCR." (PMID 34350110, 2021). "Moreover, the expression level of PCDHB17P was up-regulated in breast cancer cell lines than in the mammary epithelial cell, especially in MDA-MB-231 and MCF-7 cells." (PMID 34350110, 2021). "To evaluate the influence of PCDHB17P on breast cancer cells metastasis, we upregulated PCDHB17P expressing with the pcDNA-PCDHB17P plasmid and knocked down PCDHB17P expression in MDA-MB-231 and MCF-7 cells with shRNAs against PCDHB17P (sh-PCDHB17P-1 and sh-PCDHB17P-2)." (PMID 34350110, 2021).
breast carcinoma (continued). "The evidence provided by this study supported the instance that the PCDHB17P/miR-145-3p/MELK/NF-κB axis is implicated in the metastasis and angiogenesis of breast cancer and may be considered as a potential target for the breast cancer therapies in the future." (PMID 34350110, 2021). "In addition, the expression of PCDHB17P was negatively correlated with miR-145-3p expression in breast cancer tissues." (PMID 34350110, 2021). "Hence, these results from our study revealed that PCDHB17P/miR-145-3p/MELK/NF-κB formed a positive feedback loop in breast cancer cells." (PMID 34350110, 2021). "Based on these data, we speculated that PCDHB17P might play a role in breast cancer development." (PMID 34350110, 2021). "Our study revealed a PCDHB17P/miR-145-3p/MELK/NF-kB feedback loop network in breast cancer metastasis and angiogenesis, which gives new insights into how PCDHB17P facilitates the development of breast cancer and might provide new targets for breast cancer treatment." (PMID 34350110, 2021). "Interestingly, MELK could in turn increase the promoter activity and expression of PCDHB17P via NF-κB, thus forming a positive feedback loop that drives the metastasis and angiogenesis of breast cancer." (PMID 34350110, 2021). "To further explore the function of PCDHB17P in breast cancer, we referred to GSEA and found that PCDHB17P expression was related to angiogenesis." (PMID 34350110, 2021). "To confirmed whether PCDHB17P modulate breast cancer progression in a MELK-dependent manner, we transfected breast cancer cells stably overexpressing PCDHB17P with miR-145-3p mimics or si-MELK." (PMID 34350110, 2021). "Overall, the results demonstrated that the constitutive activation of PCDHB17P/miR-145-3p/MELK/NF-κB feedback loop promotes the metastasis and angiogenesis of breast cancer, suggesting that this lncRNA might be a promising prognostic biomarker and therapeutic target for breast cancer." (PMID 34350110, 2021).
lymph node metastasis (1 paper, 2021). "There was a significant correlation between PCDHB17P expression and age or lymph node metastasis." (PMID 34350110, 2021).
cancer (2 papers, 2021 to 2022). A tumor composed of atypical neoplastic, often pleomorphic cells that invade other tissues. "Mechanistic investigation indicated that PCDHB17P acted as a cancer-promoting competing endogenous RNA (ceRNA) by binding miR-145-3p and upregulating MELK." (PMID 34350110, 2021).